HMGB1 (high mobility group box 1)
Diseases named in the same sentence as HMGB1 in open-access papers (continued):
Sharing a sentence is not in itself a finding about the gene and the disease.
osteosarcoma (continued). "Chemotherapy-induced HMGB1 expression in osteosarcoma cells promotes autophagy to inhibit apoptosis and increase drug resistance." (PMID 25622595, 2015). "We report here that MWA induces the cardinal signs of ICD (upregulation of expression of CRT; release of ATP and HMGB1) in multiple osteosarcoma types." (PMID 25153727, 2014). "In vitro, methotrexate was reported to induce autophagosome formation accompanied by the upregulation of HMGB1 mRNA and protein levels in osteosarcoma cell lines." (PMID 24583697, 2014). "MWA for 20 min also induced significant release of ATP (P<0.001) and HMGB1 secretion (P<0.001) in all types of osteosarcoma cells." (PMID 25153727, 2014). "HMGB1 and its related signaling pathways are important targets for the treatment of osteosarcoma." (PMID 41296391, 2025). "“HMGB1 Promotes Drug Resistance in Osteosarcoma” was the most cited paper." (PMID 39655055, 2024). "Notably, “HMGB1 promotes drug resistance in osteosarcoma” emerges as the preeminent paper globally, earning acclaim from the scientific community at large." (PMID 39655055, 2024). "However, HMGA2 and HMGB1 overexpression in osteosarcoma cell lines induce resistance to cisplatin by inducing autophagy." (PMID 36614297, 2023). "Furthermore, suppressing HMGB1 effectively restored chemosensitivity in osteosarcoma cells to lower concentrations of doxorubicin." (PMID 38064181, 2023). "It was reported that anticancer agents doxorubicin induced HMGB1 upregulation in human osteosarcoma cells, and knockdown of HMGB1 restored the chemosensitivity of osteosarcoma cells in vivo and in vitro by inducing autophagy, an intracellular self-defense mechanism known to confer drug resistance." (PMID 34778055, 2021). "Also, HULC induces the progression of osteosarcoma by regulating the miR-372-3p/HMGB1 signaling axis, and HULC accelerates the growth of human liver CSCs via autophagy." (PMID 33425489, 2021). "The inhibition of HMGB1 could inhibit the proliferation and invasion of human osteosarcoma MG‐63 cells and promote apoptosis of these cells in vitro." (PMID 33140586, 2021). "Conversely, high levels of HMGB1 in osteosarcoma may induce autophagy of osteosarcoma cells, which contributes to resistance to cisplatin, doxorubicin, and methotrexate treatment." (PMID 33015161, 2020). "Next, we found that lncR-C3orf35 and HMGB1 expression was correlated with osteosarcoma metastasis." (PMID 33015161, 2020). "Furthermore, HULC acts as a ceRNA to regulate HMGB1 expression by competitively sponging miR-372-3p, thereby regulating the progression of osteosarcoma." (PMID 32188407, 2020). "Moreover, the suppression of HGMB1 expression resulted in obvious suppression of cell proliferation and invasion capacities and elevated the apoptosis rate, indicating that miR‐505 and HMGB1 can be used as potential targets of osteosarcoma." (PMID 32348630, 2020). "HMGB1 was demonstrated to stimulate cell proliferation and migration in a variety of mammalian cells including fibroblasts, airway SMCs, osteosarcoma cells, and cancer cells." (PMID 32211403, 2020). "HMGB1 has been investigated in various kinds of cancers, including osteosarcoma." (PMID 32188407, 2020). "In the current study, the detection of miR‐505 and HMGB1 in normal human bone cells and osteosarcoma cells found that miR‐505 expression was significantly lower in osteosarcoma cells than in normal human bone cells, whereas HMGB1 expression was significantly higher." (PMID 32348630, 2020). "Low expression of mir‐505 and high expression of HMGB1 were observed in osteosarcoma tumor cells." (PMID 32348630, 2020). "Overall, the nude mouse model confirmed that HULC could promote osteosarcoma tumour growth and metastasis by targeting miR-372-3p/HMGB1." (PMID 32188407, 2020).
osteosarcoma (continued). "The metastasis-free survival rate of the high lncR-C3orf35/HMGB1 expression group was lower than that of the low lncR-C3orf35/HMGB1 expression group (lncR-C3orf35: p = 0.01; HMGB1: p = 0.04), which indicated that lncR-C3orf35/HMGB1 was correlated with osteosarcoma metastasis." (PMID 33015161, 2020). "miR‐505 may inhibit the proliferation and invasion and promote apoptosis of osteosarcoma cells by targeting and suppressing HMGB1." (PMID 32348630, 2020). "Our study is the first to demonstrate that HULC may act as a ceRNA to modulate HMGB1 expression by competitively sponging miR-372-3p, leading to the regulation of osteosarcoma progression, which provides new insight into osteosarcoma diagnosis and treatment." (PMID 32188407, 2020). "Similarly, our data also revealed that carbon ion irradiation significantly promoted the release of HMGB-1 from irradiated osteosarcoma in vitro and in vivo." (PMID 30774761, 2019). "A few studies have demonstrated that HMGB1 is regulated by miRNAs in osteosarcoma." (PMID 29899164, 2018). "Taken together, our results suggest that HMGB1 may plays an important role in miR-1284 mimics-mediated reduction of osteosarcoma cell growth and metastasis." (PMID 29899164, 2018). "Long noncoding RNA (LncRNA) metastasis-associated lung adenocarcinoma transcript 1 (MALAT1), an lncRNA with notorious roles in multiple aggressive tumors, was reported to promote osteosarcoma development by up-regulation of HMGB1 via hsa-miR-142-3p and hsa-miR-129-5p." (PMID 29899164, 2018). "In addition to the included studies, there were some other researches focusing on the correlation between HMGB1 expression and patient prognosis in osteosarcoma, ovarian cancer and non-small cell lung cancer." (PMID 27391431, 2016). "In addition, HMGB1 is a critical regulator of autophagy, promoting drug resistance in osteosarcoma and leukemia cells." (PMID 25622595, 2015). "Hence, it is reasonable to suspect that methotrexate induces tumor-promoting autophagy in osteosarcoma cells by upregulating HMGB1." (PMID 24583697, 2014). "However, the immunofluorescence study showed high expression of HMGB1 in osteosarcoma." (PMID 36204682, 2022). "Furthermore, mechanistic investigations confirmed that activation of the miR-372-3p/HMGB1 regulatory loop by knockdown of miR-372-3p or overexpression of HMGB1 reversed the in vitro roles of HULC in promoting osteosarcoma cell proliferation, migration and invasion." (PMID 32188407, 2020). "In addition, we propose that HMGB1 may mediate the influence of lncR-C3orf35 on osteosarcoma prognosis through a ceRNA mechanism." (PMID 33015161, 2020). "Thus, we hypothesized that HULC might promote the development of OS by modulating the miR-372-3p/HMGB1 axis, which provides a new potential therapeutic target for osteosarcoma." (PMID 32188407, 2020). "Hence, the lncR-C3orf35/HMGB1 axis may affect the polarization of macrophages, which promotes osteosarcoma metastasis." (PMID 33015161, 2020). "In addition, HMGB1 is reported to promote drug resistance in osteosarcoma." (PMID 24944700, 2014). "This article reviews the research progress for high-mobility group protein B1 (HMGB1) and its signaling pathway in osteosarcoma (OS) and discusses its application potential in targeted therapy." (PMID 41296391, 2025). "Osteosarcoma cells dosed with 2 exhibited DAMPs consistent with ICD, such as CRT exposure on their cell membrane exterior and extracellular release of ATP and HMGB‐1." (PMID 40202773, 2025). "Actinomycin D (dactinomycin), a natural chromopeptide, promotes the release of HMGB1 and IFNG and the exposure of CALR in osteosarcoma cells." (PMID 39759512, 2024). "In vitro, emodin also significantly inhibited the proliferation of the osteosarcoma cell lines SOSP-9607, MG63 and SAOS-2, decreased HMGB1-induced VEGF production, and increased the expression of SIRT1 and deacetylase activity." (PMID 35637953, 2022).
osteosarcoma (continued). "After treated with a chemical library in osteosarcoma U2OS cells, higher levels of p-eIF2a, calreticulin (CALR), and HMGB1 were detected in U2OS cells treated with Paclitaxel/Docetaxel than in U2OS cells treated with Fluorouracil/Capecitabine." (PMID 36605427, 2022). "The result indicated that CCL28, KLF2 and TNFSF18 did not significantly affect cell apoptosis, while the knockdown of HMGB1 and TLR4 significantly increased the proportion of apoptotic of osteosarcoma cells." (PMID 36204682, 2022). "To discover the potential target genes regulated by miR-372-3p in osteosarcoma cells, we performed bioinformatics analysis with RAID v2.0 software and identified high mobility group box 1 protein (HMGB1) as one of the target genes of miR-372." (PMID 32188407, 2020). "The expression of HMGB1 in HOS, 143B, MG‐63, and U20S cells was significantly higher than that in hFOB1.19 cells in patients with osteosarcoma (P < 0.001)." (PMID 32348630, 2020). "Human osteosarcoma U2OS cells expressing CALR-red fluorescent protein (RFP), green fluorescent protein (GFP)-LC3 or HMGB1-GFP fusion proteins were treated with each of these compounds at a concentration that is high enough to induce off-target effects (10 μM)." (PMID 30940805, 2019). "In conclusion, our results exhibited that miR-1284 is able to target HMGB1, inhibiting the cell proliferation and migration, and suppress EMT of the osteosarcoma." (PMID 29899164, 2018). "Resistance of osteosarcoma cell lines to Dox, Cis and methotrexate has been shown to be due to the induction of autophagy by the DNA-binding protein HMGB1 (high mobility group box 1)." (PMID 27582507, 2016). "Exposing mouse osteosarcoma K7M2 cells to microwaves for a sublethal ablation time has been shown to increase surface expression of CRT as well as the release of ATP and HMGB1." (PMID 25153727, 2014). "A subsequent clinical study, which performed an expression profile analysis on genes regulating cell proliferation, metastasis, and DR in canine osteosarcoma patients, found that MGST1 and HMGB1 genes were overexpressed in dogs with MDR as in humans with other tumors." (PMID 40563676, 2025). "GFP-tagged mutant HMGB1 transgenes were transiently expressed in human osteosarcoma (U2OS) cells, and the nucleolar dynamics were quantified as the ratio of mobile versus immobile fractions of GFP–HMGB1 in nucleoli using fluorescence recovery after photobleaching (FRAP)." (PMID 40468084, 2025). "In addition, HMGB1 promotes the resistance of osteosarcoma to chemotherapy in vitro, and overexpression of miR-22, which targets the 3′ untranslated region (UTR) of HMGB1, inhibits HMGB1 function and reverses the resistance of tumor cells to chemotherapy." (PMID 34599143, 2021). "However, no report ever describes the regulatory role of miR-1284 in osteosarcoma or its correlation with HMGB1 in any carcinogenesis." (PMID 29899164, 2018).
acute kidney injury (57 papers, 2009 to 2026). Sudden and sustained deterioration of the kidney function characterized by decreased glomerular filtration rate, increased serum creatinine or oliguria. "In cardiac surgery patients at high risk for postoperative acute kidney injury, increased HMGB1 and Sema5b levels after RIPC were associated with renal protection after surgery." (PMID 35727636, 2022). "Recent research has demonstrated that cytoplasmic HMGB1 can exacerbate inflammation-associated cellular injury by activating renal tubular ferroptosis following I/R injury, highlighting HMGB1 as a promising therapeutic target for acute kidney injury (AKI)." (PMID 40335466, 2025). "HMGB1 has a significant involvement in the progression of post-contrast acute kidney injury (PC-AKI)." (PMID 39008169, 2024). "Extracellular HMGB1 drives cellular damage and inflammatory cascades in renal ischemic reperfusion injury (IRI) and plays a pivotal role in acute kidney injury (AKI) onset via Tumor Necrosis Factor (TNF)-α/HMGB1 inflammatory signalling." (PMID 39840112, 2024). "Circulating HMGB1 levels are elevated in acute kidney injury (AKI) patients and bears strong correlation with proteinuria and leukocyte count." (PMID 39682695, 2024). "We aimed to estimate serum high mobility group protein 1 (HMGB1) levels in hepatitis B virus-related acute-on-chronic liver failure patients and analyze their clinical value in the development and outcomes of Acute kidney injury." (PMID 36712653, 2022). "HMGB1 is also involved in renal disease including acute kidney injury because HMGB1 can promote kidney injury through the TLR4 pathway." (PMID 34341389, 2021). "The present study was conducted from the perspective of M1 macrophage activation to explore the effect of the TNF‐α/HMGB1 pathway on pyroptosis in liver failure and acute kidney injury." (PMID 32419317, 2020). "Among the specific morbidity endpoints, death and the incidence of renal failure were significantly different in relation to the tertile distribution of post-CPB HMGB1 concentrations." (PMID 32286371, 2020). "It was reported that necrotic tubular cells release high-mobility group box-1 (HMGB-1), which induces further inflammatory response through activation of nuclear factor kappa B (NF-κB) leading to acute kidney injury (AKI)." (PMID 32695255, 2020). "In detail, among the assessed composite of morbidity endpoints, HMGB1 concentrations showed statistical significance for predicting the mortality and renal failure." (PMID 32286371, 2020). "It was also found that melatonin promoted renal regeneration in acute kidney injury and alleviated circadian rhythm disruption by inhibiting the distribution of HMGB1." (PMID 31607859, 2019). "Increased levels of for example serum IL-6, IL-10, and HMGB-1 were reported in pigs and mice in more severe models of local inflammation such as multiple trauma and acute kidney injury." (PMID 27250718, 2016). "In addition, since mortality was associated with acute renal failure and shock, the plasma levels of AGE, sRAGE, HMGB1, and S100A12 were used to analyze the presence and absence of acute renal failure and shock." (PMID 35723375, 2022). "In addition, the inhibition of the TNF-α/HMGB1 inflammatory signaling pathway suppresses macrophage pyroptosis to improve liver and kidney function during acute kidney injury and acute liver failure." (PMID 34749650, 2021). "HMGB1 is known to play an important role in the development of acute kidney injury." (PMID 34341389, 2021). "The TNF-α/HMGB1 inflammation signaling pathway plays an important role in pyroptosis during liver failure and acute kidney injury (AKI)." (PMID 37426664, 2023). "Similarly, high HMGB1 levels involved septic patients who developed acute kidney injury (AKI)." (PMID 36498479, 2022).
acute kidney injury (continued). "This prospective, observational study demonstrates that patients with high serum HMGB1 concentrations 1 h after weaning from CPB were associated with a significantly increased risk of developing composite of morbidity endpoints after cardiac surgery, renal failure and death in particular." (PMID 32286371, 2020). "However, the effect of GSPE on the HMGB1, and the relationship of those two with acute kidney injury and chronic kidney fibrosis are unknown." (PMID 27690015, 2016). "In lactate‐induced acute kidney injury, p300/CBP acts as ‘writers’ to catalyse HMGB1‐Kla and promotes the release of HMGB1 into the extracellular space via exosomes." (PMID 40984037, 2025). "In addition, HMGB1 plays multiple roles in the inflammatory response in DN; some studies have reported that HMGB1 plays an important role in the development of DN, lupus nephritis, ANCA-associated vasculitis kidney damage, acute kidney injury and interstitial nephritis." (PMID 37065747, 2023). "In addition, a recent study showed that quercetin was able to reduce the inflammatory response of cells in the contrast-induced acute kidney injury (CI-AKI) model via downregulation of HMGB1 protein expression." (PMID 36421424, 2022). "As PC-AKI is classified as acute kidney injury, HMGB1 might be a factor in the development of PC-AKI." (PMID 34341389, 2021). "HMGB1 and IL-6 plasma levels were higher in patients with a higher Sequential Organ Failure Assessment (SOFA) score (> 10), and the presence of septic shock or acute kidney injury." (PMID 33939645, 2021). "For example, mice lacking HMGB1 are protected from post-ischemic acute renal failure because tubular cell necrosis no longer triggers post-ischemic renal inflammation and tubular damage." (PMID 33732235, 2021). "Hence, in addition to the TNF‐α inhibitors or neutralizing antibodies that are currently used for treatment, a combination of HMGB1 inhibitors or TNF‐α SNPs can also be considered for the treatment of liver failure and acute kidney injury." (PMID 32419317, 2020). "In addition to HMGB1, histones released from damaged renal cells in acute kidney injury (AKI) triggered neutrophil recruitment and renal inflammation via interaction with TLR2 and TLR4, in turn activating MyD88, NF-κB and mitogen activated protein kinase (MAPK) signaling." (PMID 32731558, 2020). "Similarly, ALA alleviated acute kidney injury (AKI) in CLP rats by inhibiting NF-κB; downregulating proinflammatory cytokines (TNF-α, IL-6, IL-1β), iNOS, and HMGB1 expression in renal tissues; and reducing serum blood urea nitrogen (BUN) and creatinine levels." (PMID 40699721, 2025).